RAG2 (recombination activating 2)
Diseases named in the same sentence as RAG2 in open-access papers (continued):
Sharing a sentence is not in itself a finding about the gene and the disease.
T-cell acute lymphoblastic leukemia (4 papers, 2013 to 2025). Acute lymphoblastic leukemia of T-cell origin. "Combining cDNA microarray and ChIP-seq analysis, we identify Rag1 and Rag2 as novel Notch1 transcriptional targets in acute T-cell lymphoblastic leukemia (T-ALL) cells." (PMID 34322489, 2021). "Using rag2 promoter (target to immature T-cell), Langenau generated MYCC-induced T cell acute lymphoblastic leukemia in zebrafish." (PMID 23554972, 2013).
teratoma (4 papers, 2016 to 2018). A non-seminomatous germ cell tumor characterized by the presence of various tissues which correspond to the different germinal layers (endoderm, mesoderm, and ectoderm). "After intramyocardial transplantation of maGSCs, we found now a reduced frequency and a reduced size of teratomas in T and B-cell-deficient RAG2−/− recipients compared to additionally NK cell-deficient RAG2−/−γc−/− mice." (PMID 28220117, 2017). "In this study, we have observed a higher teratoma formation rate when undifferentiated so-called multipotent adult germline stem cells (maGSCs) were transplanted into the heart of T, B, and natural killer (NK) cell-deficient RAG2−/−γc−/− mice than in RAG2−/− mice, which still have NK cells." (PMID 28220117, 2017). "To investigate whether NK cells indeed have effects on the teratoma growth in the heart as they have after subcutaneous injections, we injected 5 × 105 undifferentiated maGSCs into the myocardium of RAG2−/− mice that are deficient in T and B lymphocytes but have functional NK cells." (PMID 28220117, 2017). "The teratomas were also smaller with a mean length of 1.3 mm and a mean width of 0.8 mm than those in the CsA-untreated RAG2−/−γc−/− mice (P < 0.001)." (PMID 28220117, 2017). "Compared to the tumors of the RAG2−/−γc−/− mice, the size of teratomas in RAG2−/− mice was smaller with a mean size of 3.6 mm length and 2.3 mm width." (PMID 28220117, 2017). "Interestingly, Rag2/Pfp dKO mice successfully formed teratoma from the identical source of human iPS cells." (PMID 29050212, 2017). "These RAG2 SCID pigs successfully formed human iPS-derived teratoma whereas Rag2-/- mice or IL2RG-/Y mutated pigs failed to form teratoma." (PMID 29050212, 2017). "Moreover, additional teratomas at distant sites occurred in 75% of the RAG2−/−γc−/− recipients." (PMID 28220117, 2017). "Human teratomas that developed in the RAG2 knockout SCID pigs also had a higher prevalence of CD45+ and CD34+ cells in the teratoma than in SCID mice." (PMID 30560086, 2018). "The treatment with CsA led to a highly significant decrease of the teratoma frequency in RAG2−/− and RAG2−/−γc−/− mice in comparison to the untreated animals (P = 0.0019, χ2 test)." (PMID 28220117, 2017). "Very recently, we successfully transplanted human inducible pluripotent stem cells or porcine trophoblast stem cells into biallelic RAG2 SCID pigs, and produced teratoma from allogenic or xenogeneic cells." (PMID 27463006, 2016). "In the RAG2−/− mice treated with CsA, no teratomas were observed in the myocardium but in one mouse, a tumor was found on the heart." (PMID 28220117, 2017). "The tumors in RAG2−/− mice also contained derivatives of the three embryonic germ layers, including intestinal epithelium, striated muscles, cartilage, and neural tissues, and were therefore teratomas (data not shown)." (PMID 28220117, 2017).
thymic lymphomas (4 papers, 2010 to 2024). "We observed that 19 out of 49 P1A Tg mice in Rag2-deficient background developed thymic lymphoma after 7 months of age." (PMID 20976169, 2010).
amyloid (3 papers, 2023 to 2024). "For example, complete depletion of adaptive immunity through a knockout of the Rag2 gene showed either beneficial or detrimental effects in 5xFAD and APP/PS1 models of amyloidosis that were linked to amyloid plaque load and microglial activation." (PMID 38600001, 2024). "Previous work has found opposite effects of Rag2-/- immunodeficiency on amyloid plaque pathology and cellular responses." (PMID 37708272, 2023).
Anxiety (3 papers, 2023 to 2025). Intense feelings of nervousness, tension, or panic often arise in response to interpersonal stresses. "Reconstituted Rag2-/- also showed less anxiety behavior than naïve Rag2-/- mice, as measured by time in the open arm of an elevated plus maze." (PMID 36827449, 2023). "The depressive and anxiety-like behavior exhibited by Rag1–/– or Rag2–/– mice lacking T cells can be improved by transplantation of splenocytes/lymphocytes from chronically stressed mice, and immunization with myelin-related peptides can further reduce stress-induced anxiety." (PMID 37156764, 2023).
asthma (3 papers, 2011 to 2017). "If lack of IFNγ production by NK cells was causing the enhanced asthma phenotype observed in γc deficient mice, then we would expect to see the same phenotype in NK cell depleted RAG2−/− mice." (PMID 23940740, 2013). "In order to track the exogenous in vivo primed T cells that we were transferring into these mice and to prevent interference of TH1 cells, we used STAT6 or IL-4Rα deficient mice on a RAG2-/- background for our asthma experiments." (PMID 22014099, 2011). "Since T cells play a critical role in initiating and propagating asthma and γc−/− mice lack T-cells, we used an asthma model wherein we provided in vivo-primed OVA-specific OT-II T cells to γc–sufficient RAG2−/−, γc−/−, or γcxRAG2−/− mice using a previously established transfer model." (PMID 23940740, 2013). "We examined whether naïve CD4+ T cells or in vivo primed CD4+ T cells isolated from DO11.10x RAG2-/- would be more suitable for this asthma model." (PMID 22014099, 2011). "To induce asthma pathophysiology in the mouse model, we performed adoptive transfer experiments of OVA-transgenic IFN-γ-treated WT and Irf1−/− Th9 cells into Rag2−/− mice and subsequently challenged the mice with nebulized OVA." (PMID 28497800, 2017).
B cell lymphoma (3 papers, 2022 to 2023). "The present study shows that PFOA, PFOS, PFNA and PFHxS cause a time- and concentration-dependent downregulation of RAG1 and RAG2 gene expression in the human B cell lymphoma Namalwa cell line." (PMID 36326898, 2022).
Chronic colitis (3 papers, 2008 to 2020). A chronic inflammatory disease of the large intestine (colon, cecum and rectum). "In the validation study using anti-IL-17A antibody, chronic colitis was induced in all the Rag2−/− mice that received T cells." (PMID 31941937, 2020). "Finally, adoptive transfer of naïve CD62LhiCD4+ T cells into Rag-2-/-Spp-1-/- mice resulted in less chronic colitis than Rag-2-/- recipient mice." (PMID 31291255, 2019).
diabetes (3 papers, 2013 to 2026). "Next, mCD47-INS-1E or cont-INS-1E cells were injected into the peritoneal cavity of Rag2−/− γ chain −/− mice with streptozotocin-induced diabetes; the blood glucose levels of these mice were monitored for 7 days." (PMID 23472187, 2013).
endometriosis (3 papers, 2015 to 2025). The growth of functional endometrial tissue in anatomic sites outside the uterine body. "Studies had reported endometriosis was induced in BALB/c-Rag2(-/-) IL2RG (-/-) mice by surgical implantation of human endometrial fragments." (PMID 40830889, 2025). "After inducing endometriosis, the RAG2–/– mice (ILC2 intact), RAG2–/–αCD90.2 mice (ILC2 depleted), and RAG2–/–IL-2rγ–/– mice (ILC2 deficient) were treated with PBS and IL-33." (PMID 34699382, 2021). "Endometriosis was induced using human endometrium in β-estradiol-primed BALB/c-Rag-2-/-Il2rγ-/- mice receiving intraperitoneal injections of ABT-898 (25 mg/kg) or 5% dextrose control for 21 days." (PMID 25811892, 2015).
glioma (3 papers, 2016 to 2025). A benign or malignant brain and spinal cord tumor that arises from glial cells (astrocytes, oligodendrocytes, ependymal cells). "The role of RAG1 and RAG2 in glioma cells, as well as the precise mechanisms underlying the regulation of RAGs in glioma, is currently being investigated in detail in our laboratory." (PMID 41362770, 2025). "We were interested in determining if RAG1 and RAG2 interact with each other such as lymphoid cells and can form a complex within the glioma cells." (PMID 41362770, 2025). "This coordinated expression of RAG1 and RAG2 indicates that they share a common regulatory mechanism and possible co-dependency in glioma cells." (PMID 41362770, 2025). "Our investigation provided compelling evidence affirming the expression of RAG1 and RAG2 in glioma cell lines, such as U251, U87, T98G, A172, U118, and LN229." (PMID 41362770, 2025). "Further immunofluorescence (IF) analysis was performed to evaluate the expression of RAG1 and RAG2 at the intracellular level in two glioma cell lines." (PMID 41362770, 2025). "Firstly, we assessed the expression levels of RAG1 and RAG2 across a series of glioma cell lines, U251, U87, T98G, U118, and LN229." (PMID 41362770, 2025). "Importantly, we also observed that RAG1 present in the glioma cells could interact with RAG2, and it could catalyze a significant level of pathogenic recombination between conventional 12RSS and 23RSS within the glioblastoma cells, which was dependent on the activity of RAGs present in the cells." (PMID 41362770, 2025). "To investigate the expression pattern of RAG1 and RAG2 in patients with glioblastoma, we analyzed RNA-seq data of 693 patient samples obtained from the Chinese Glioma Genome Atlas (CGGA) database." (PMID 41362770, 2025). "We showed the coexpression and interaction of RAG1 and RAG2 in glioma cells; however, the upstream regulatory mechanisms leading to their reactivation in the non-lymphoid cells are yet to be elucidated." (PMID 41362770, 2025). "While our study provides strong evidence for the expression of RAG complex (RAG1/RAG2) in glioma cells and cleavage at cryptic RSS within fragile regions leading to chromosomal rearrangements, there are certain limitations." (PMID 41362770, 2025). "In summary, using various molecular biology techniques, we show that RAG1 and RAG2 proteins are expressed in different glioma cell lines, although the overall expression level was lower than the pre-B cell lines." (PMID 41362770, 2025). "In conclusion, our findings provide compelling evidence for the role of RAG1 and RAG2 in the generation of chromosomal deletions and rearrangements within glioma cells." (PMID 41362770, 2025). "While the Rag2-null model is permissive to different flank-implanted cancer cell lines, including glioma-derived U87MG cells, the more specific intracranial implantation of cancer cells has not yet been characterized." (PMID 36483050, 2022). "Importantly, we established that both RAG1 and RAG2 are expressed in glioma cells, form a complex, and play a pivotal role in the generation of chromosomal deletions and rearrangements." (PMID 41362770, 2025). "This suggests that both RAG1 and RAG2 are differentially expressed across glioma cell lines." (PMID 41362770, 2025). "Besides, RAG1 and RAG2 expression were lower in glioma cell lines compared to the Nalm6, a pre-B cell line." (PMID 41362770, 2025). "However, no RAG1 or RAG2 was detected in the pull-down samples using the control DNA substrate lacking the 12RSS sequence, further confirming the specific binding of the RAG complex to the 12RSS substrate in the U87 glioma cell line." (PMID 41362770, 2025).
graft versus host disease (3 papers, 2015 to 2022). An immune system disorder that occurs after allogeneic hematopoietic stem cell transplant and is a reaction of donor immune cells against host tissues. "This study also assessed gene expression profiling in skin of a sclerodermatous graft-versus-host disease (scl GVHD) model in Rag2–/– mice, which were found to also exhibit the IL-13 pathway activation resembling that in SSc patients of inflammatory subset." (PMID 26106387, 2015).
intestinal tumors (3 papers, 2007 to 2016). "In Helicobacter hepaticus/AOM-induced intestinal tumors, IL-22 released by ILCs supported the growth of intestinal tumors in T and B cell-deficient Rag2−/− mice." (PMID 27148488, 2016). "Recent studies have indicated that chronic inflammation caused either by infection with Helicobacter pylori or Helicobacter hepaticus is a prerequisite for intestinal tumor development in Smad3-/- and Tgfb1-/-; Rag2-/- mice, respectively." (PMID 17615082, 2007).
liver cancer (3 papers, 2020 to 2022). An epithelial or non-epithelial malignant neoplasm that arises from the liver. "Rag2-Il2rg double-knockout mice with liver cancer were intravenously administered paOAd followed by blue light irradiation using an implantable blue LED device." (PMID 32703933, 2020).
liver failure (3 papers, 2018 to 2021). A liver disease characterized by the liver losing or has lost all of its function. "Results showed that fumarylacetoacetate hydrolase (Fah) deficiency led to liver failure, and double knock out of Rag2 and the gamma chain of the IL-2 receptor resulted in sufficient human liver cell repopulation in mice." (PMID 29511142, 2018). "A chimeric mouse model was constructed using FRG (Fah-/-/Rag2-/-/Il2rg-/-) mice, in which liver failure can be induced at will." (PMID 29511142, 2018). "Here, Fah–/–Rag2–/–IL2rg–/– (FRG) rats are generated by CRISPR/Cas9, showing accelerated liver failure and lagged liver xeno‐repopulation compared to FRG mice." (PMID 34382351, 2021).
periodontitis (3 papers, 2013 to 2023). An acute or chronic inflammatory process that affects the tissues that surround and support the teeth. "In this study, we further explored the role of ILC3s in periodontitis-associated bone loss using Rag2-/- and Rag2-/-Il2rg-/- mice." (PMID 38015204, 2023). "Therefore, our findings suggest that ILC3s, which are differentially impacted by Rag2-/-Il2rg-/- and Rag2-/- mutations, may be primarily responsible for human periodontitis-like cervical alveolar bone resorption near the site of gingival inflammation." (PMID 38015204, 2023).
psoriasis (3 papers, 2016 to 2024). An autoimmune condition characterized by red, well-delineated plaques with silvery scales that are usually on the extensor surfaces and scalp. "Using a humanized mouse model of psoriasis, transplantation of unaffected skin from a patient with psoriasis was grafted onto mice deficient in type I and type II interferons and the recombination activating gene 2, (IFNG-/- IFNAR-/- RAG2-/-) and the skin graft spontaneously developed psoriasis." (PMID 34012438, 2021). "However it was also shown that immune-compromised HIV patients exhibit the same rate of psoriasiform dermatitis as the general population and that a complete inactivation of Rag2 in a JunB/JunC mouse psoriasis model did not prevent the development of the disease." (PMID 27050272, 2016).
pulmonary fibrosis (3 papers, 2014 to 2019). Chronic progressive interstitial lung disorder characterized by the replacement of the lung tissue by connective tissue, leading to progressive dyspnea, respiratory failure, or right heart failure. "Of note, radiation-induced pulmonary fibrosis was more severe in recombination-activating gene 2 (RAG2)-deficient mice that lack mature T- and B-lymphocytes suggesting that lymphocytes may have beneficial effects." (PMID 31024543, 2019). "In contrast, lung fibrosis upon whole thorax irradiation was aggravated in recombination-activating gene 2 (RAG2)-deficient mice; these mice lack mature T- and B-lymphocytes suggesting that lymphocytes may also have beneficial effects in radiation-induced lung disease." (PMID 24766907, 2014).
rhabdomyosarcoma (3 papers, 2016 to 2025). A rare aggressive malignant mesenchymal neoplasm arising from skeletal muscle. "To asses which function of PRL-3 enhances solid tumor progression, we used a transgenic zebrafish model of rhabdomyosarcoma (RMS) driven by rag2:KRASG12D, which enables real-time visualization of tumor initiation and growth." (PMID 40463094, 2025). "Applied to the Tg(rag2:KRASG12D) model, this elegant strategy shows that rhabdomyosarcoma are composed of distinct cell populations that are dynamically reorganized during tumor growth." (PMID 32759814, 2020). "Thus, the ectopic expression properties of the zebrafish rag2 promoter in the mesenchymal cell compartments has been used to drive expression of KRASG12D or a myristoylated constitutively active form of Akt2 in order to generate transgenic models of rhabdomyosarcoma or liposarcoma, respectively." (PMID 32759814, 2020).
alopecia (2 papers, 2019 to 2023). Hair loss usually from the scalp. "Rag2-/- mice that received splenocytes isolated from WT animals immunized with rDSG1 spontaneously developed a disease phenotype, characterized by few erosions and a high extent of alopecia and erythema, evaluated by the PV score." (PMID 37237515, 2023). "Intriguingly, Rag2 KI mice displayed milder immunological phenotypes than Rag2 KI/EGFP mice and there were no clues to the determinants of OS phenotypes including severe alopecia, B cell numbers, and elevated IgE levels in Rag2 KI mice." (PMID 30872621, 2019). "We could not observe any symptoms related to alopecia and erythroderma with age in Rag2 KI mice." (PMID 30872621, 2019).
antibody deficiency (2 papers, 2015 to 2021). "Hypomorphic mutations in other IEI genes (BTK, GATA2, IL2RG, JAK3, RAG1, RAG2, etc.)have been previously found in patients with antibody deficiency and milder phenotypes or in CVID patients." (PMID 34975878, 2021). "We report herein a novel presentation of leaky RAG1/RAG2 deficiency which is associated with selective IgG antibody deficiency and massively decreased numbers of naïve CD4+ T-cells." (PMID 26186701, 2015).
bone tumour (2 papers, 2014 to 2025). "We developed a novel orthotopic and humanised bone tumour microenvironment model in highly immunocompromised Il2rg and Rag2 double knockout rats." (PMID 41315643, 2025). "In this study we have developed preclinical orthotopic models of Ewing sarcoma and other primary and metastatic bone tumours by injecting cells directly into the femur of young NSG or Rag2−/− γc−/− mice." (PMID 24409320, 2014).
Cachexia (2 papers, 2020 to 2024). Severe weight loss, wasting of muscle, loss of appetite, and general debility related to a chronic disease. "The wasting syndrome and skeletal phenotype associated with SHIP1 deficiency were ameliorated in immunodeficient mice lacking RAG2 and IL2RG." (PMID 38388173, 2024).
colorectal cancer (2 papers, 2013 to 2021). A primary or metastatic malignant neoplasm that affects the colon or rectum. "RAG2 deficient mice do not develop mature T and B lymphocytes and when infected with Helicobacter hepaticus develop all the progressive stages of colorectal carcinoma (CRC)." (PMID 23474627, 2013).
COVID-19 (2 papers, 2022). A disease caused by infection with severe acute respiratory syndrome coronavirus 2. "On the other hand, a higher COVID-19 mortality rate in specific monogenic DNA repair defects (such as RAG1/RAG2, DNMT3B deficiencies) exists based on the current observation." (PMID 35713311, 2022).